IL6 (interleukin 6)
Diseases named in the same sentence as IL6 in open-access papers (continued):
Sharing a sentence is not in itself a finding about the gene and the disease.
COVID-19 (continued). "Moreover, COVID-19 patients with more severe symptoms have higher concentrations of IL-6 at admission." (PMID 35126355, 2021). "The exacerbated inflammation that is also found in severe COVID-19 cases is mediated especially through the uncontrolled production of pro-inflammatory cytokines such as interleukin-6 (IL-6), interleukin-8, monocyte chemoattractant protein-1 (MCP-1), and TNF-α in the cytokine release syndrome." (PMID 33968948, 2021). "Vitamin D may also help to reduce the severity of inflammatory reactions by inhibiting pro-inflammatory cytokines such TNF-α and IL-6, which are involved in the development of cytokine storm in COVID-19-related ARDS." (PMID 34884440, 2021). "It has been shown that the level of IL-6 positively correlates with the severity of COVID-19." (PMID 34689776, 2021). "Although these compounds were not common in TCM, it is of note that they could have a potential in treating COVID-19 based on their favorable affinity with IL-6." (PMID 33146673, 2021). "Indeed, IL-6 levels and kynurenine/tryptophan ratios were among the top predictors of mortality in COVID-19 patients, confirming previous targeted analyses of our larger, independent cohort." (PMID 34571942, 2021). "Several publications on SARS-CoV-2 report a strong association between high serum IL-6 levels (>80 pg/mL in serum) and severe disease progression or CNS involvement in COVID-19, even in the absence of respiratory symptoms." (PMID 34650454, 2021). "Interestingly, Jain and co-authors analysed the vitamin D level in both asymptomatic and critically ill COVID-19 patients and its correlation with inflammatory markers (IL-6; TNF-α, and serum ferritin)." (PMID 33530467, 2021). "In this context, targeting the IL-6 pathway could be an innovative therapeutic approach for COVID-19 patients, particularly in the elderly." (PMID 34836187, 2021). "Finally, C5a, C3a, factor P, and serum IL-1β, IL-6, and IL-8 levels positively correlated with critical COVID-19 in-hospital deaths." (PMID 34276659, 2021). "The association of male sex, high IL-6, and ARDS could explain the higher mortality of patients with critical COVID-19." (PMID 34208922, 2021). "Recent studies have found that the production of IL-1β, IL-18, TNF-α, and IL-6 was high in severe COVID-19 patients especially those with severe respiratory failure and are linked to the cytokine storm; these cytokines are downstream of the TLR4 canonical MyD88-dependent pathway." (PMID 33505220, 2021). "Focused analysis of 14 cytokines classically upregulated in COVID-19 patients revealed that only some of these cytokines are dysregulated in lung tissue, whereas the other cytokines are upregulated in extrapulmonary tissues (e.g. IL6 and IL2RA)." (PMID 34262555, 2021). "Clinical reports have shown that increased levels of IL-6 are related to COVID-19 pathogenesis." (PMID 34064553, 2021). "Severe COVID-19 patients show an expressively higher serum IL-6 than those with mild infection." (PMID 34220807, 2021). "The unique lipid composition of ProLungTM budesonide, may play a role in the innate immune system and may decrease IL-6 levels which can be markedly elevated in COVID-19." (PMID 34766166, 2021). "Other markers analyzed (WBC, PLR, IL-6) were not significantly different between controls and COVID-19 patients nor associated with GI symptoms." (PMID 34753964, 2021). "Therefore, IL-6 is a biomarker to predict COVID-19 severity, and also fatal outcomes both in the general SARS-CoV-2 infected population and in COVID-19 patients with obesity." (PMID 33809913, 2021). "Also, in COVID-19, IL-6 is one of the key cytokines driving the immunopathology caused by the prolonged aspecific inflammation and correlated symptoms." (PMID 33550983, 2021). "Early consideration for corticosteroid therapy and possibly anti-IL-6 drugs may improve the adverse COVID-19 prognosis in diabetic patients." (PMID 34384426, 2021).
COVID-19 (continued). "Specifically, IL-6 has been associated with cytokine release in ARDS, septic shock, and COVID-19." (PMID 34207152, 2021). "Although our studies were not specifically designed to identify the mechanisms that drive peripheral blood MT-DNA accumulation, significant correlations between LDH and IL-6 with MT-DNA levels point to a potential deleterious role for cellular necrosis in COVID-19 pathophysiology." (PMID 33444289, 2021). "Data from various clinical studies and meta-analyses confirmed the applicability of the infection-mediated clinical biomarkers IL-6, VEGF-D, SAA, CRP, serum ferritin, and PCT as prognostic and adjunct diagnostic indicators for developing electrical-based COVID-19 biosensors." (PMID 34205852, 2021). "IL-6 antibodies such as tocilizumab have been found to have efficacy in the treatment of COVID-19." (PMID 34721573, 2021). "IL-6 (proinflammatory) and IL-10 (anti-inflammatory) are two cytokines commonly dysregulated in COVID-19 patients and the ratio of IL6-to-IL10 may be used to predict outcomes of COVID-19 patients." (PMID 33780352, 2021). "We believe it would be crucial to include Gal-9 in a predictive model of COVID-19 patients and mortality since several large cohort studies have demonstrated that D-dimer and IL-6 in addition to clinical factors predict mortality in hospitalized COVID-19 patients." (PMID 33947753, 2021). "Our identified IL-6/JAK/STAT3 signaling is associated with CKDs and severity of COVID-19." (PMID 34067609, 2021). "As such, in COVID-19 patients, miR-766-3p reduction may represent a biomarker of increased IL-6 expression or, more interestingly, may itself have anti-inflammatory function." (PMID 34564316, 2021). "This speculation has been supported by the clinical results obtained from the treatment of severe COVID-19 with tocilizumab, a monoclonal antibody targeting IL-6 pathways." (PMID 34373739, 2021). "Finally, one clinical characteristic (chest distress) and five laboratory findings (IL-6, TNI, PCT, CRP, Ca) were identified as the most predictive risk factors for prognostic prediction of severity for patients with moderate COVID-19." (PMID 33390780, 2021). "Given such an immune system imbalance, patients with thyroid autoimmune diseases might undergo a worse clinical course of COVID-19 due to higher baseline levels of serum IL-6 and TNF alpha compared to healthy individuals." (PMID 33765288, 2021). "Inflammation mediated by IL-6 is also thought to be closely linked to elevated ferritin levels found in non-survivors with severe COVID-19." (PMID 34178414, 2021). "Temporal expression of IL-6 was compared between severe and moderate illness with COVID-19." (PMID 34775962, 2021). "The overactive immune response and nonspecific, disseminated cytokine release, including interleukin-6 (IL-6), in severe cases of COVID-19 may lead to organ failure." (PMID 33780352, 2021). "Similarly, the RECOVERY consortium recently demonstrated that biologic IL-6 inhibitors decrease mortality and requirement for invasive ventilation in COVID-19 patients already treated with corticosteroids." (PMID 33692097, 2021). "Several studies shared the same findings: elevated IL-6 levels existed in biological fluids of COVID-19 patients, and IL-6 might serve as a predictive biomarker for severity of COVID-19 infection." (PMID 37287491, 2021). "To conclude, the further use biobank method seems suitable for investigating COVID-19 cytokine-related research questions, but variation on IL-17A, IL-6 and IL-12p70 levels might have been introduced by the applied delay in processing." (PMID 34289718, 2021). "The utility may be further increased as we see increasing usage of IL-6 inhibitors for COVID-19 management where CRP monitoring becomes obsolete." (PMID 34572701, 2021). "IL-6 was found to be consistently elevated in COVID-19 patients with respiratory failure." (PMID 34745662, 2021).
COVID-19 (continued). "In some cases of patients with aspergillosis, an increased level of IL6 is noticed (in epithelial cells), suggesting that a co-infection of COVID-19 may contribute to the severity of this clinical feature, owing to the augmented level of cytokines." (PMID 34575758, 2021). "Thus, the potential of anti-IL-6 therapy as a therapeutic modality in treating severe COVID-19 requires further investigation." (PMID 33557330, 2021). "Additionally, high-sensitivity C-reactive protein–albumin ratio (HsCAR) and low prognostic nutritional index (PNI) and the ratio of interleukin (IL)-6 to IL-10 were reported to be related to the prognosis of COVID-19 patients." (PMID 34217339, 2021). "The excessive synthesis of interleukin-6 (IL-6) is related to cytokine storm in COVID-19 patients." (PMID 34960054, 2021). "For instance, significant differences in the frequency of use of antivirals and interleukin-6 antagonists between patients with mild-to-moderate and severe COVID-19 could have affected the cardiac outcome." (PMID 33481096, 2021). "Consistent with previous publications 15-17, SARS-CoV-2 infection was also found to activate interleukin-6 (IL-6)-mediated signaling, which contributes to cytokine release syndrome in severe COVID-19, with representative genes of this pathway including SOCS3 and IL6." (PMID 34104087, 2021). "However, despite the ubiquitous role of IL-6 in different types of infections, when we assessed the predictive value, this marker, IL-6, behaves as a valued predictor of COVID-19 progression." (PMID 34576798, 2021). "Of note, the percentages of both IL-6 and uric acid levels in survived COVID-19 patients were above 90%, suggesting that they might be good specificity for indicators of mortality in COVID-19 patients." (PMID 33679237, 2021). "It is even reported that the immune dysregulation is driven by IL-6 in COVID-19." (PMID 33602326, 2021). "Furthermore, in a study of a small number of children with pediatric multisystem inflammatory syndrome or COVID-19, plasma IL-18 levels were increased in addition to IL-6 levels." (PMID 33841434, 2021). "Finally, IL-1ra and IL-6 levels were significantly higher in severe versus mild COVID-19 patients, while PDGF decreased." (PMID 34675240, 2021). "Anti-TNF-alpha antagonists etanercept and adalimumab could be also administrated in moderate COVID-19 with pneumonia in order to downregulate IL-1 and IL-6 levels as potential endpoints." (PMID 34205487, 2021). "Tocilizumab is a monoclonal antibody targeting interleukin-6 receptor (IL-6R), inhibiting signal transduction and, thus, counteracting the effects of pro-inflammatory interleukin-6 (IL-6), that was shown to be involved in inflammatory storms in severe COVID-19." (PMID 32804279, 2021). "Furthermore, IL-6 levels were correlated with the viral load and disease progression, evidenced by CT in severe COVID-19 patients and was proposed as a possible prognostic biomarker for the forthcoming cytokine storm and severe disease." (PMID 34207266, 2021). "Severely ill patients hospitalised with COVID-19 exhibit increased levels of many cytokines, including Interleukin (IL)-1β, IL-2, IL-6, IL-7, IL-8, IL-10, IL-17, granulocyte colony stimulating factor (G-CSF), monocyte chemoattractant protein 1 (MCP-1) and tumor necrosis factor (TNF)." (PMID 34205262, 2021). "Indeed, elevated levels of CCL2, CXCL10, IL-6 and TNFα have been identified in severe COVID-19 patients compared to patients with a mild form of the disease." (PMID 34452468, 2021). "However, the levels of CRP, IL-6, and D–dimer in the severe COVID-19 group with hypertension were significantly elevated than in the normotensive severe COVID-19 group (P < 0.05)." (PMID 33869774, 2021).
COVID-19 (continued). "In agreement with other studies, we found that IL-6 and TNFα were elevated in the COVID-19 cohort compared to the control subjects [median (IQR), all units picograms per milliliter; IL-6: 4.65 (3.32–9.16) vs 0.69 (0.55–0.89), p < 0.001; TNFα: 4.49 (1.87–8.03) vs 0.04 (0.04–0.84), p < 0.001]." (PMID 34792686, 2021). "Interestingly, recent studies have demonstrated that in the cytokine storm, a situation observed in severe COVID-19, the systemic levels of IL-6 and IL-10 are increased in the same way." (PMID 33717074, 2021). "Interestingly, challenge of this prediction model with data from the second wave achieved an accuracy of 0.83; 95% CI: (0.68, 0.93), sensitivity of 0.88 and specificity of 0.73, indicating IL-6 as the best predictor of COVID-19." (PMID 34675240, 2021). "Novel anti-TNFα and anti-IL-6 cannabis extracts can be useful additions to the current anti-inflammatory regimens to treat COVID-19, as well as various rheumatological diseases and conditions, and ‘inflammaging’ - the inflammatory underpinning of aging and frailty." (PMID 33465050, 2021). "Severe cases were associated with significantly increased levels of ferritin and IL-6, which suggested that in some pregnant women with severe COVID-19, sHLH may be diagnosed." (PMID 34439868, 2021). "Given this potential association between post-corticosteroid IL-6 levels and COVID-19 severity, we hypothesized that the glucocorticoid receptor (GR or NR3C1) may be coupled to IL-6 expression in specific cell types that govern cytokine release syndrome (CRS)." (PMID 33723251, 2021). "The higher levels of interleukin-6 have been also correlated with the severe cases of COVID-19." (PMID 34656134, 2021). "Importantly, severe cases of COVID-19 are identified as uncontrolled inflammatory response known as cytokine storm where IL-6, IL-1β, IL-10, and IFN-γ have been found to be significantly higher." (PMID 35250966, 2021). "Although findings from the clinical trials do not support the widespread use of IL-6 antagonists/inhibitors in hospitalized patients with mild-to-moderate COVID-19, the use of IL-6 antagonists/inhibitors can produce a beneficial outcome when utilized in patients with severe disease." (PMID 34066983, 2021). "On the one hand, IL-6 binds to membrane IL-6 receptor (IL-6R) and induces the production of acute-phase proteins such as CRP and fibrinogen, biomarkers associated with poor COVID-19 outcomes." (PMID 34276355, 2021). "Increased serum interleukin-6 and LDH levels could be associated with worse outcome in COVID-19 patients." (PMID 33730058, 2021). "IL-6 concentrations are increased 2.9-fold in patients with complicated COVID-19 vs. uncomplicated." (PMID 33466589, 2021). "IL-6 levels strongly correlated with plasma desmosine (p = 0.0017), which remained significant after adjustment for age and gender (p = 0.023), suggesting a key link between inflammation and pulmonary/vascular tissue damage in COVID-19." (PMID 35111793, 2021). "For example, genetic variations in IL-6 signalling could affect both the presentation of COVID-19 and the response to an anti-IL6 treatment." (PMID 34512643, 2021). "Moreover, patients with severe COVID-19 who have been administered anti–IL-6 treatments have reported having higher numbers of secondary infections." (PMID 33445810, 2021). "Our data demonstrate elevated activity of the inflammatory cytokines IL-1β and IL-6 in COVID-19 in blood and tissues and demonstrate the utility of cytokine transcriptional response modules in providing a dynamic readout of the activity of these pathways in vivo." (PMID 33319166, 2021). "However, the concentration of IL-6 was significantly higher in moderate COVID-19 and severe cases of COVID-19 groups compared to control and recovered groups indicating it to be an independent predictor in the coronavirus disease." (PMID 33914789, 2021). "Additionally, the IL-6 levels were higher in patients who died from COVID-19 than in the recovered individuals." (PMID 34276659, 2021).
COVID-19 (continued). "Increased interleukin-6 levels in COVID-19 patients may induce differentiation of Th17 cells and stimulate cytokine storm, inflammation, and pulmonary dysfunction." (PMID 34946266, 2021). "Interestingly, very recently, interleukin-6 antibodies tocilizumab and sarilumab have shown to improve outcome in COVID-19 patients under mechanical ventilation." (PMID 34385593, 2021). "Therefore, surveillance of IL-6 is helpful in the early screening and timely intervention for severe COVID-19 patients." (PMID 33390771, 2021). "We propose that IL-1β and IL-6 transcriptional response modules provide a dynamic readout of functional cytokine activity in vivo, aiding quantification of the biological effects of immunomodulatory therapies in COVID-19." (PMID 33319166, 2021). "Strikingly, our study, and two recent investigations carrying out single cell RNA sequencing of immune cells and cytokine determinations in BAL, converge in a major pathogenic role of IL-1 β, IL-6, and CCL2 in patients who develop severe COVID-19 compared to people with less severe disease." (PMID 33995342, 2021). "The characterization of COVID-19 pathophysiology highlighted the decisive role of IL-1β and IL-6." (PMID 34012390, 2021). "Furthermore, activation of TRPV-1 boosts the release of various pro-inflammatory molecules, including neuropeptides substance P (sP) and cytokines such as interleukin 6 (IL-6), the same involved in the pathophysiological events affecting the COVID-19." (PMID 34805220, 2021). "However, to date, results from the main randomized clinical trials on hospitalized patients with COVID-19 treated with the anti-IL-6 mAb, tocilizumab, remain controversial." (PMID 33550983, 2021). "However, in epithelial cells from BALs of patients infected with COVID-19, IL-6 or TNF mRNAs were barely detectable." (PMID 33585804, 2021). "Which inflammatory cytokine is most important in the pathogenesis of COVID-19 is currently unknown, although IL-6 appears to be crucial." (PMID 34479631, 2021). "Additionally, inflammation-related molecules, including MCP-1 and interleukin 6 (IL-6), were enriched in severe COVID-19 kidneys, especially in the distal tubules." (PMID 34136484, 2021). "In particular, IL-6 level was the highest in severely ill COVID-19 patients." (PMID 34012410, 2021). "In addition, IL6 has been identified as a clinical early warning indicator for severe and critically ill patients in the diagnosis and treatment protocol for COVID-19 (Trial Version 8)." (PMID 34731090, 2021). "IL-18 was correlated with markers of the severity of COVID-19, such as IL-6 and LDH." (PMID 34539644, 2021). "COVID-19 patients in particular display elevated levels of IL-6, and this is the cytokine so far mostly studied, with investigations also on the possible therapeutic use of anti-IL-6 agents, such as tocilizumab." (PMID 34646263, 2021). "Olokizumab, a humanized anti-IL6 IgG4 (R-Pharm International), was approved in May 2020, for patients suffering from severe COVID-19 respiratory distress." (PMID 33668613, 2021). "As have been reported, IL-6 and IL-8 levels increased with the severity of COVID-19 and mortality." (PMID 34938289, 2021). "Moreover, the ROC analysis showed that the ability of the AUC of IL-6 to predict disease severity was one of the highest, demonstrating its predictive power for the severity of COVID-19 patients over the course of hospitalisation." (PMID 34439469, 2021). "Indeed, a retrospective review has demonstrated that treating COVID-19 cases with LMWH decreases IL-6 overproduction, thus being an important therapeutic choice to be considered, once inflammation and coagulopathies are closely related." (PMID 33968948, 2021). "Analysis of plasma from patients with COVID-19 has revealed increases in cytokines, including IL-1β, IL-2, IL-6, IL-7, IL-10, TNFα, monocyte chemoattractant protein (MCP1/CCL2), granulocyte colony stimulating factor (G-CSF), and macrophage inflammatory protein 1α (MIP1α/CCL3)." (PMID 34251989, 2021).